MALAT1 (metastasis associated lung adenocarcinoma transcript 1)
Diseases named in the same sentence as MALAT1 in open-access papers (continued):
Sharing a sentence is not in itself a finding about the gene and the disease.
breast cancer (continued). "Of these, lincFOXF1 had previously been shown to inhibit osteosarcoma cell invasion, migration, and metastasis in vitro and in vivo, whereas MALAT1 overexpression in breast cancer was found to suppress metastasis in a range of transgenic, syngeneic, and xenograft models." (PMID 36217480, 2022). "It has been observed that LINC MALAT1 has a similar promoting effect on the growth and invasion of colorectal cancer tumor cells as the liver cancer in this study, but has diametrically opposite results in the growth and invasion of glioma and breast cancer." (PMID 35706002, 2022). "However, MALAT1 is highly expressed in various cancers, including liver, lung, and breast cancer, and plays a role in cancer progression." (PMID 35546353, 2022). "Moreover, MALAT1 enhanced docetaxel resistance in breast cancer cells by reducing miR-200b expression." (PMID 35951366, 2022). "A recent study revealed that MALAT1 also acts as a tumor suppressor gene in breast cancer." (PMID 35557985, 2022). "LncRNA MALAT1 binds and inactivates the prometastatic transcription factor TEAD, preventing TEAD from associating with its co‐activator YAP and target gene promoters in breast cancer cells." (PMID 35608100, 2022). "Similarly, the xenograft model study found downward expression of lncRNA MALAT1, which resulted in breast cancer metastasis suppression." (PMID 36685962, 2022). "In addition, targeted inactivation of the MALAT1 gene in a transgenic mouse model has also been used to study the role of lncRNA MALAT1 in breast cancer." (PMID 35656102, 2022). "lncRNA, MALAT1, is a suppressor of breast cancer tumor metastasis by binding and inactivating TEAD." (PMID 34429400, 2021). "In breast cancer for example, lncRNAs nuclear paraspeckle assembly transcript 1 (NEAT1), metastasis-associated lung adenocarcinoma transcript 1 (MALAT1), and non-coding RNA in the aldehyde dehydrogenase 1A pathway (NRAD1), have all been described as oncogenic and dysregulated in breast cancer." (PMID 34072264, 2021). "In this study, we demonstrated that MALAT1 was up-regulated under hypoxia in breast cancer cells." (PMID 34012919, 2021). "Also, an animal model is needed to confirm the role of the MALAT1/miR-3064-5p pathway in breast cancer." (PMID 34012919, 2021). "Furthermore, a meta-analysis showed that high expression of MALAT1 in breast cancer is correlated with unfavorable disease-free survival (DFS) and recurrence-free survival (RFS)." (PMID 34527584, 2021). "Since MALAT1 was mainly in the cytoplasm of breast cancer cells, we hypothesized that MALAT1 may serve as a miRNA sponge." (PMID 34012919, 2021). "MALAT1 is related to the poor clinical prognosis of patients with breast cancer." (PMID 34308750, 2021). "MALAT1 has been widely investigated for its role in breast cancer." (PMID 33987091, 2021). "We found that MALAT1 was also up-regulated in hypoxia in breast cancer cells." (PMID 34012919, 2021). "Therefore, the purpose of this study was to explore the regulatory mechanisms and functions of MALAT1 in breast cancer cells." (PMID 34012919, 2021). "Several other studies also confirmed the inhibitory function of MALAT1 in breast cancer." (PMID 34308750, 2021). "Lastly, functional assays revealed that MALAT1 could promote cellular migration and proliferation of breast cancer cells." (PMID 34012919, 2021). "Previous experiments have verified that MALAT1 plays a key role in breast cancer." (PMID 34113575, 2021). "Another study demonstrated that MALAT1 could enhance the proliferation and invasion of breast cancer cells by altering the histone 3 lysine 4 (H3K4) epigenotype to activate the EEF1A1 promoter." (PMID 34527584, 2021). "However, one previous report showed opposite results, and claimed that the MALAT1 lncRNA suppresses metastasis in breast cancer, suggesting that further convincing evidence is required to clarify this discrepancy." (PMID 34638541, 2021).
breast cancer (continued). "Lastly, functional assays revealed that MALAT1 could promote breast cancer cell aggressiveness, by increasing proliferation and migration and altering cell cycle distribution." (PMID 34012919, 2021). "The LINC00276&MALAT1/miR-206/FZD4-Wnt7b pathway was identified which may be useful in future research on targets against breast cancer metastasis and recurrence." (PMID 34457116, 2021). "Moreover, ligand-receptor interactions and potential regulatory mechanisms showed that LINC00276&MALAT1/miR-206/FZD4-Wnt7b is a potential pathway in the functions of IMAAGs in breast cancer metastasis and recurrence." (PMID 34457116, 2021). "For instance, lncRNA MALAT1 can inhibit breast cancer metastasis." (PMID 33558499, 2021). "MALAT1 act as a metastasis-suppressing lncRNA in breast cancer." (PMID 35111811, 2021). "In addition, the serum levels of HOTAIR, MALAT1, PAI-1, and OPN were also reported to have a diagnostic power of 98%, 72%, 80%, and 86% in discriminating breast cancer from fibroadenoma patients." (PMID 33670447, 2021). "Moreover, the high level of MALAT1 in breast cancer has been demonstrated and was related to tumor stage and size in other studies." (PMID 34308750, 2021). "In addition, the findings of this study provide information on the oncogenic and tumor-suppressive functions of MALAT1 in breast cancer cells." (PMID 34457116, 2021). "MALAT1, a nuclear lncRNA, is also a tumor suppressor in breast cancer." (PMID 33860799, 2021). "However, oncogenic and tumor-suppressive functions of MALAT1 in breast cancer cells are controversial." (PMID 34457116, 2021). "The LINC00276&MALAT1/miR-206/FZD4-Wnt7b pathway was also identified which may be useful in future research on targets against breast cancer metastasis and recurrence." (PMID 34457116, 2021). "Therefore, regulating the expression of MALAT1 would be a valuable means to repurposing metformin in breast cancer treatment." (PMID 34164906, 2021). "Previously, we identified three novel MALAT1 enhancers that form distinct long-range chromatin-chromatin interactions with each other and the MALAT1 promoter in breast cancer cells under normoxic and/or hypoxic conditions, which are not observed in non-tumorigenic cells." (PMID 34019552, 2021). "Further investigation is needed to confirm the role of MALAT1 in circulating breast cancer cells." (PMID 33573289, 2021). "Furthermore, a series of lncRNAs have been elucidated to serve as important prognostic hallmarks in numerous tumors, for instance, MALAT1 in breast cancer and digestive system cancer, XIST in various solid tumors, BCAR4 and SNHG16 in diverse human neoplasms." (PMID 33639865, 2021). "Moreover, specifically targeting cheRNA MALAT1 by antisense oligonucleotides (ASOs) can significantly reduce tumor volume, induce cell differentiation, and inhibit metastasis in a mouse mammary carcinoma model." (PMID 33937246, 2021). "Mechanistically, PTEN up-regulates MALAT1 expression by binding and sequestering miR-17, miR-20a and miR-106b, and MALAT1 suppresses colorectal and breast cancer cell migration and invasion by reducing the pro-metastatic Epithelial Cell Adhesion Molecule (EpCAM) and ITGB4." (PMID 32174966, 2020). "In breast cancer, knockout of MALAT1 induced the metastatic ability." (PMID 32929060, 2020). "They examined MALAT1 expression in 78 breast cancer patients and observed significant upregulation of MALAT1 in cancerous tissues compared with the paired no-cancerous tissues, and an association of high MALAT1 expression with lymph metastasis and shorter DFS in breast cancer tissues." (PMID 32708561, 2020). "Interestingly, an alternatively spliced transcript Δsv-MALAT1 appeared as an independent factor for a good prognosis in breast cancer patients." (PMID 32872162, 2020). "The nuclear export of FOXO1 by elevated pAkt and leading to loss of control MALAT1 at its promoter might be a mechanism for MALAT1 mediated resistance and cell invasion in HER2+ breast cancer cells." (PMID 32708561, 2020).
breast cancer (continued). "However, the upregulation of MALAT1 is more significantly associated with HER2+ cells that are resistant to trastuzumab, and with metastatic TNBC in breast cancer cells." (PMID 32708561, 2020). "Thus, MALAT-1 is a promising biomarker for predicting survival outcomes in patients with breast cancer." (PMID 32700729, 2020). "To investigate whether MALAT1 plays a role in the metabolism of PCa-derived cells, we measured the lactate produced in 5 prostate and one breast cancer-derived cell line upon MALAT1 depletion." (PMID 33375130, 2020). "Subcutaneous injection of MALAT1 antisense oligonucleotides could effectively downregulate the MALAT1 expression in the tumor site and result in a formation of cystic and poorly metastasizing tumors in the luminal B breast cancer mouse model." (PMID 33293956, 2020). "These seemingly contradictory findings may implicate the complexity and intricacies of the roles of MALAT1 in breast cancer metastasis." (PMID 32929060, 2020). "MALAT1 is a potential biomarker for predicting trastuzumab resistance in HER2+ breast cancer." (PMID 32708561, 2020). "Furthermore, NEAT1 and MALAT1, lncRNAs often deregulated in breast cancer, were also occupied by RUNX1 both in interphase and mitosis." (PMID 32655837, 2020). "Multiple studies have suggested that MALAT-1 plays oncogenic roles in breast cancer." (PMID 32700729, 2020). "As a cancer-promoting factor, MALAT1 is closely related to certain biological characteristics such as vascular epithelialization, migration and distant metastasis, postoperative fever, and systemic inflammatory response in breast cancer." (PMID 33362863, 2020). "In our study, high MALAT-1 expression levels were associated with low immune cell infiltration (e.g., CD4+ and CD8+ T cells), which may explain the correlation between MALAT-1 and poor prognosis in patients with breast cancer." (PMID 32700729, 2020). "In breast cancer, many lncRNAs such as MIAT (myocardial infarction-associated transcript), SNHG1 (small nucleolar RNA host gene 1), and MALAT1 (metastasis-associated lung adenocarcinoma transcript 1) have been reported to participate in the occurrence, progression, and metastasis of tumors 27-29." (PMID 31892853, 2020). "Our current study suggests that MALAT1 could be a biomarker for predicting response to trastuzumab in HER2+ breast cancer." (PMID 32708561, 2020). "MALAT1 fusion genes were previously detected in breast cancer and ovarian cancer samples." (PMID 31745703, 2020). "For instance, lnc MALAT1 has been reported to promote proliferation and inhibit apoptosis through derepressing Rap1B by sponging miR-101 in glioma cells, while it is also confirmed to inhibit breast cancer metastasis as a metastasis suppressor." (PMID 32735016, 2020). "LncRNA MALAT1 expression inversely correlates with the progression and metastasis of breast cancer." (PMID 33231563, 2020). "Importantly, compared with control PyMT mouse mammary tumors, MALAT1-deficient PyMT mouse mammary tumors exhibit increased YAP-TEAD target gene expression and tumor metastasis, which can be reversed by genetic MALAT1 add-back." (PMID 32174966, 2020). "Hence, the role of MALAT-1 and its influence on survival outcomes in patients with breast cancer remain controversial." (PMID 32700729, 2020). "Moreover, dysregulation of MALAT1 expression has been indicated in various cancers, including breast cancer." (PMID 32486413, 2020). "In summary, the data from our study support the oncogenic role of MALAT1 in breast cancer." (PMID 32708561, 2020). "Evidence from clinical studies for a role for MALAT1 in breast cancers has been accumulating." (PMID 32708561, 2020). "Data from our study demonstrates the oncogenic role of MALAT1 in breast cancer." (PMID 32708561, 2020). "However, some knockdown studies using antisense oligonucleotide (ASO) of MALAT1 in breast cancer cell lines and animal models demonstrated impaired cell migration, and significantly reduced metastasis." (PMID 32929060, 2020).
breast cancer (continued). "Some studies have shown that elevated MALAT-1 expression levels contribute to breast cancer carcinogenesis, whereas a few studies have demonstrated that MALAT-1 may serve as a tumor-suppressing gene." (PMID 32700729, 2020). "Therapeutic targeting of the PI3K/Akt pathway and nuclear retention of FOXO1 could suppress the upregulation of MALAT1, re-sensitize the sensitivity of trastuzumab, and prevent breast cancer progression." (PMID 32708561, 2020). "Interestingly, however, a significant inhibition of both macro and micrometastases formation was observed in mammary carcinoma mouse model with MALAT1 knock-out, making MALAT1 a promising target in cancer therapy." (PMID 32369931, 2020). "Specific antisense oligonucleotides treatment targeting MALAT1 could inhibit the growth of mammary carcinoma or metastasis of human non-small cell lung cancer, respectively." (PMID 32082313, 2020). "However, another study reported that down-regulation of MALAT1 in breast cancer cells induced epithelial–mesenchymal transition (EMT) and promoted the metastasis of breast cancer cells through the PI3K/Akt signaling pathway." (PMID 30683807, 2019). "A regulatory mechanism of the MALAT1/miR-216b-5p/PNPO axis may be important in breast cancer development." (PMID 30982780, 2019). "Meanwhile, patients with higher MALAT1 expression had a worse prognosis in breast cancer." (PMID 30683807, 2019). "Therefore, the aim of the present study was to explore the role of MALAT1 in breast cancer oncogenesis and its potential value as a prognostic biomarker." (PMID 30683807, 2019). "In summary, the relationship of MALAT1 and breast cancer remains elusive." (PMID 30683807, 2019). "MALAT1/miR-216b-5p/PNPO may act as competing endogenous RNAs (ceRNAs) that affect the biological behavior of breast cancer cells and cancer progression." (PMID 30982780, 2019). "For the clinic-pathological correlation analysis, 1086 breast cancer patients within TCGA were divided into two groups: high MALAT1 group (n=169) and low MALAT1 group (n=917) by adopting the gene-specific threshold of MALAT1 expression in breast cancer tissues as a cut-off value." (PMID 30683807, 2019). "Additionally, we demonstrated that TALAM1 cooperates with MALAT1 in the regulation of the properties guiding breast cancer aggressiveness and malignancy." (PMID 31382922, 2019). "MALAT1 can competitively bind to miR-1, which reduces the ability of miR-1 to inhibit Cdc42, ultimately increasing the level of Cdc42 and inducing cell migration and invasion to promote breast cancer metastasis." (PMID 30754684, 2019). "Moreover, high estrogen was shown to suppress invasion of breast cancer cells through decreasing MALAT1 level." (PMID 31500187, 2019). "It was highly expressed clinically in many types of cancers such as breast cancer, non-small cell lung cancer and prostate cancer, which indicated that MALAT1 may play an important role in the occurrence and development of tumors." (PMID 30683807, 2019). "MALAT1 is a typical lncRNA that is markedly up-regulated in breast cancer." (PMID 30683807, 2019). "The positive correlation detected between MALAT1 and TALAM1 suggests that TALAM1 could share a biological role in the progression of human breast cancer, as reported for MALAT1." (PMID 31382922, 2019). "It is necessary to study more in-depth regulatory mechanisms of MALAT1 in breast cancer, which will help us to understand whether it can be used as a potential diagnostic or prognostic indicator and gene therapy target." (PMID 30683807, 2019). "Altogether, these results suggested that expressions of both MYC and CD47 were positively regulated by MALAT1 in triple negative and Her-2 positive breast cancers, which implied that MALAT1 might get involved in immune escape of breast cancer cells." (PMID 29416769, 2018).
breast cancer (continued). "The evidence that Malat1 is a tumor suppressor in breast cancer is seemingly contrary to many studies investigating its functions in other types of cancer, such as lung, in which it was first identified and subsequently titled accordingly (“Metastasis-Associated Lung Adenocarcinoma Transcript 1”)." (PMID 29912916, 2018). "LncRNA Malat1, one of the down-regulated lncRNAs following propofol sedation, was a highly conserved lncRNA that has been found in various cancers, such as non-small cell lung cancer and breast cancer, and plays a role in the proliferation of myocardial cells." (PMID 29628875, 2018). "Therefore, MALAT1 is not only a potential target for treating Luminal B breast cancer, but would be also applicable to triple-negative and Her-2 positive breast cancers." (PMID 29416769, 2018). "MALAT1 is oncogenic in breast cancer, and it upregulates the WNT/β-catenin (CTNNB1) pathway." (PMID 30545127, 2018). "Through the Oncomine data portal (Oncomine.org) we found support for this hypothesis, which indicated Malat1 is reduced in both ductal and lobular breast cancer morphological subtypes compared to control normal breast tissue." (PMID 29912916, 2018). "Notably, we have demonstrated in our study that genetic interventions with MALAT1 are effective for inhibiting proliferation and invasion abilities of triple-negative and Her-2 positive breast cancer cells." (PMID 29416769, 2018). "Hence, high expressions of MALAT1 were closely related to metastasis and relapse of both kinds of breast cancer." (PMID 29416769, 2018). "MALAT1 is, among lncRNAs, a stable and highly transcribed molecule localized in the nucleus, and it has been reported that, in breast cancer cells expressing ERα, 17β-estradiol treatment negatively regulates MALAT1 transcription, thus inhibiting proliferation, migration and invasion." (PMID 30319549, 2018). "Recently, a study published in NEJM has indicated that ASO-mediated silencing of MALAT1 in a metastasis luminal B breast cancer model can result in a cystic, poorly metastatic phenotype that closely mimicked those that arose in animals with genetic deletion of Malat1." (PMID 29416769, 2018). "The authors also reported that in TCGA RNA seq data, MALAT1 was “underexpressed in human breast tumors compared with normal breast tissue”, and that lower MALAT1 levels correlated with shorter distant metastasis-free survival in all breast cancer, as well as in luminal A and basal breast cancer." (PMID 30545127, 2018). "In summary, this project provides further clarity concerning the function of Malat1, specifically in breast cancer, while also indicating that the Nischarin expression context is an important factor in the determining how Malat1 activity is governed in breast cancer." (PMID 29912916, 2018). "The lncRNA MALAT1 is found in exosomes from breast cancer patients." (PMID 30545127, 2018). "However, MALAT1 was demonstrated to suppress the EMT of breast cancer through inhibiting the PI3K-AKT pathway." (PMID 29368602, 2018). "MALAT1 overexpression in breast cancer (BC) has been reported by different research groups." (PMID 29739426, 2018). "The consistent differential expression suggested that MALAT1 could potentially act as an oncogene in our breast cancer tissues." (PMID 28938549, 2017). "However, when crossed with the MMTV-PyMT mouse model of human breast cancer, Malat1 deletion impaired tumour progression as evidenced by a severe reduction in metastatic burden." (PMID 28747406, 2017). "Our previous studies have reported that miR-124 inhibited CDK4 expression in breast cancer cells, therefore, we testes whether MALAT1 inverted the inhibitory effect of miR-124 on CDK4 expression." (PMID 26918449, 2016). "However, the miR-124 inhibitor rescued MALAT1-siRNA-respressed proliferation in breast cancer cells." (PMID 26918449, 2016). "MALAT1 is also an abundantly expressed lncRNA in primary breast cancer." (PMID 27191888, 2016).